NOTCH1 (notch receptor 1)
Diseases named in the same sentence as NOTCH1 in open-access papers (continued):
Sharing a sentence is not in itself a finding about the gene and the disease.
tumor (continued). "One patient (St23784/17) had amplifications in the 3q, 6q, 8q, 9q, and 10q22.1 regions of stemness gene localization in her tumor (the following genes were amplified: SOX2, MYC, KLF4, NOTCH1, NODAL)." (PMID 32523653, 2020). "On the molecular level, the ALDH+ tumor has higher expression of Notch-1 and EMT markers than ALDH− tumor." (PMID 33344242, 2020). "We also confirmed that C-JUN regulates NOTCH1 expression using a luciferase reporter assay and demonstrated that JNK-IN-8 repressed tumor growth in a TNBC xenograft mouse model via inhibition of CSC properties, including NOTCH1 and ALDH1 expression." (PMID 32283767, 2020). "In consequence, genetic and pharmacological blockade of Notch1 is able to revert the increase in CSC markers expression, mammosphere formation, and tumor-initiating ability, all induced during TORC1/2 inhibition treatment." (PMID 31379945, 2019). "To better understand how our model, and more broadly, NOTCH1 signaling relates to human CRC, we generated transcriptome-wide expression profiles from tumor tissue (consisting of epithelium and stroma)." (PMID 31526760, 2019). "Aberrant functioning of Notch-1, Wnt/β-catenin, and STAT3 proteins and their crosstalk signaling pathways have been found to be involved in tumor survival, drug resistance, and relapse." (PMID 31357721, 2019). "Conversely, miR-34a experimental induction exerts tumor suppressive effects in CSCs by inhibiting BCL2 Apoptosis Regulator (BCL2) and NOTCH1/NOTCH2 genes and boosting DNA damage responses." (PMID 31450858, 2019). "Overall, we demonstrate that Nanog signaling induces tumor cell radioresistance and stimulates ALDH activity, most likely through activation of the Notch1 and Akt pathways." (PMID 30845764, 2019). "Our findings provide direct evidence that Notch1 pathway promotes GIC self-renewal, invasion and tumor growth through PI3K pathway activity via upregulating CXCR4 expression." (PMID 31382985, 2019). "Overexpression of activated NOTCH1 and its downstream target MYC in mouse lung produced tumours that recapitulated the SCC-distinguishing metabolism." (PMID 31114017, 2019). "Western blots were used to verify the activation of Notch1/CXCR4/AKT pathway in self-renewal, invasion and tumor growth of GICs." (PMID 31382985, 2019). "Grouping analysis was used to further evaluate the correlation between Notch1 signaling and other clinical features of PTC and revealed that Notch1 signaling was closely correlated with tumor size, capsule invasion and clinical stage in patients with PTC." (PMID 30622441, 2019). "Most of them promote tumour development, e.g., cell cycle activators (c-Myc and CDK4/6), anti-apoptotic factor (Bcl2), activators of invasion (c-Met, Notch1 and Fra-1) and epithelial-mesenchymal transition inducing factor (SNAIL)." (PMID 31658284, 2019). "In a HNSCC heterotopic xenograft tumor model, treatment with the epidermal growth factor receptor (EGFR) blocker Cetuximab inhibits angiogenesis by downregulating Notch1 and Hypoxia-inducible factor 1 alpha (Hif1α) subunit." (PMID 30917608, 2019). "Curcumin downregulates Notch1, which in turn inhibits NF-κB activation, resulting in a blockage of the downstream targets VEGF and CyclinD1, involved respectively in tumor-angiogenesis and proliferation." (PMID 30917608, 2019). "Relative mRNA expression of NOTCH1 and 3 and HES1 mRNA was significantly lower in tumor compared with in normal tissue." (PMID 29533972, 2018). "They showed that SLUG facilitated E-cadherin repression (through Notch1 inhibition) and inhibition of HEYL blocked tumor growth and metastasis, showing JAG1-Notch1-SLUG dependency." (PMID 30515368, 2018). "Taken together, our findings demonstrate that POFUT1 is a tumor activating gene during CRC development, which positively regulates CRC tumor progression through activating Notch1." (PMID 30250219, 2018).
tumor (continued). "STAT3, Notch1/2, Cullin1, TGF-B2, and CREBBP mediate tumor cell proliferation and therapeutic resistance, and inhibition of the Notch and TGF families sensitizes cancer cells to radiation therapy." (PMID 30546829, 2018). "With NOTCH1-driven T-ALL mouse model, many miRNAs with oncogenic or tumor suppressive roles in T-ALL onset and progression have been elucidated." (PMID 29435192, 2018). "If NOTCH1 signalling inhibits HMGA1 in vivo, we would expect an anti-correlation between NOTCH1 activity and HMGA1 expression in human tumour samples." (PMID 29743479, 2018). "We found that knocking down Notch1 remarkably reduced while overexpressing Notch1 increased the percentage of CD3+CD8+ CTL and NK cells in tumor-DLNs." (PMID 29301578, 2018). "Most studies on human CRC demonstrate that Notch-1 is elevated in human CRC tissues and correlated with poor differentiation, tumor progression and poor survival." (PMID 30323897, 2018). "Previously, suppression of Notch1 activity was shown to result in effective reduction of EMT in vitro and tumor metastasis in vivo." (PMID 30405889, 2018). "In NSCLC cell lines, it has been reported that the expression of the active form of Notch1 (Notch1 intracellular domain, NICD1) leads to increased proliferation activity, malignant transformation, and tumor growth." (PMID 29416684, 2018). "The aberrant expression of Notch1 elicits EMT and tumor progression in cancer cells through Slug, a Snail family member and a direct downstream target of Notch160." (PMID 30038258, 2018). "In a recent study, we found that anti-Notch2 treatment can reduce both HCC and ICC tumor load induced by AKT and neuroblastoma RAS viral oncogene homolog (NRas) oncoproteins, whereas Notch1 suppression decrease HCC and augments ICC occurrence." (PMID 29545603, 2018). "Perhaps this is the first report unravel the tumor suppressive property of miR-92a in gastric cancer, and the downstream signaling pathway involving EP4/Notch 1 signaling regulated by NF-κB." (PMID 29849934, 2018). "Notch1 overexpression promotes MM cells growth and results in up‐regulation of VEGF expression, promotion of tumor growth, and increased microvessel density." (PMID 29214735, 2018). "We found a dramatic upregulation of the canonical NOTCH1 target gene HEYL and a concurrent downregulation of HMGA1 and HMGA2 in fibroblasts co-cultured with JAG1-expressing tumour cells, particularly A549 and Hep3B cells." (PMID 29743479, 2018). "We further demonstrated that inhibition of Notch1 signaling by a gamma-secretase inhibitor (GSI) reduced ATL tumor cell proliferation and tumor formation in a xenograft mouse model of ATL." (PMID 30231940, 2018). "Expressions of Notch 1 and Jagged1 were positively correlated with p-STAT3 levels in primary tumor tissues." (PMID 29849934, 2018). "Conditional activation of NOTCH1/2 in CD8 T-cells induces a robust and sustained anti-tumor response, resulting in increased IFNγ production and reduced tumor burden." (PMID 30967879, 2018). "While Notch1 activation and EMT were detected at the invasive tumor front, SCC cells with epithelial characteristics were commonly present in xenograft tumors, 4NQO-induced tumors, and human SCC samples." (PMID 29170450, 2017). "While there are numerous other genes that control cell proliferation, NOTCH1 and KLF15 were very mature and classical genes in cell proliferation studies especially in the area of tumor investigation." (PMID 28388563, 2017). "MYC is the most prominent Notch target gene in NOTCH1-dependent T-ALL, and its contribution to T-ALL cell proliferation and tumor maintenance is well established." (PMID 29023469, 2017). "Remarkably, this CTC-subset displayed tumor stem-like features, as evidenced by the expression of key stem-like genes including Bmi1, CD44, Oct4, Notch1, Wnt3a, Stat3, and HIF-1α." (PMID 27738343, 2017).
tumor (continued). "Most known oncogenes (e.g. EGFR, FGFR1, MYC, ERBB2) or tumor suppressors (e.g. CDKN2A, NOTCH1) were detected to reside within the focal SCNA regions." (PMID 29348864, 2017). "In this study, 28 NOTCH1 mutations were identified and nearly 40% of these NOTCH1 mutations were predicted to truncate the gene product, again suggesting that NOTCH1 may function as a tumor suppressor gene rather than an oncogene in this tumor type." (PMID 31093353, 2017). "We demonstrate that Notch1 activation and EMT are coupled to promote tumor initiation and intratumoral cancer cell heterogeneity in SCC." (PMID 29170450, 2017). "Our results show that only KLF4, NOTCH1, and OCT3/4 were down-regulated in the whole tumor compared with normal kidney samples." (PMID 29383160, 2017). "We compared the difference of Notch1 existing in primary HCC tissues and in adjacent liver tissues and found that Notch1 is up-regulated highly in over 50% of tumor tissues and most tested HCC cell lines, identical to other reports." (PMID 28423575, 2017). "Rather, our work has uncovered prominent oncogenic roles for NOTCH1 in regulating the balance between ERMS self-renewal and differentiation, prominently impacting overall tumor growth." (PMID 28614716, 2017). "Later, this network was further expanded by adding a feed forward loop between NOTCH1 and c-MYC that was regulated by the tumor suppressive miRNA, miR-30a." (PMID 28270163, 2017). "The authors identified CD45- CD90+ CTCs in 91% of samples and demonstrated that this cell population expressed key stem-like genes including Bmi1, CD44, Oct4, Notch1, Wnt3a, Stat3, and HIF-1a compared to CD90+ tumor-tissue cells." (PMID 27738343, 2017). "Here, we demonstrate that Notch1 activation and epithelial–mesenchymal transition (EMT) are coupled to promote SCC tumor initiation in concert with transforming growth factor (TGF)-β present in the tumor microenvironment." (PMID 29170450, 2017). "The relative expression of mRNA of Notch1, VEGF, Delta4, HES1 and HEY1 were decreaced (P < 0.05) in tumor tissue which treated with chlorogenic." (PMID 28855037, 2017). "Taken together, these data indicate that TGFβ functions as a critical positive effector of Notch1 and EMT in the context of the tumor microenvironment." (PMID 29170450, 2017). "Overall, results are defensive of DEAE-Dextran as an emerging anti-tumor agent with mechanisms pertaining to β-interferon induction with probable VEGF and NOTCH1 inhibition as well as apoptosis which still needs to be studied in further depth." (PMID 29311933, 2017). "HD105, a bispecific antibody, effectively inhibits angiogenesis and tumor growth by specifically blocking the VEGF/VEGFR2 and Dll4/Notch1 signaling pathways." (PMID 28881855, 2017). "The expression of Notch1 were decreaced, PTEN, p-PTEN, p-AKT were increced significantly in tumor tissue which treated with chlorogenic (P < 0.05)." (PMID 28855037, 2017). "Altogether, these data demonstrate that LINC00152 exerts tumor-promoting functions in CRC, at least partly, through sponging miR-139-5p and then regulating NOTCH1." (PMID 29180678, 2017). "In this study, we showed that autophagy promotes the degradation of the Notch1 intracellular domain via the phosphorylation of the T2512 residue by MEKK1, and therefore suppresses tumor cell growth and migration." (PMID 27806347, 2016). "In this context, it has been shown that Notch1 and its ligand Jagged1 are strongly expressed in HRS cells, with pathway activation induced by the latter accelerating tumor cell growth and inhibiting arsenic-induced apoptosis." (PMID 26934331, 2016). "NOTCH1, HES1, and p300 expression was significantly higher in HOTAIR-overexpressing xenograft tumours." (PMID 27323817, 2016). "To confirm our observation in HCC cell lines, we investigated the expression level of Notch1, Jagged1 and Dll4 in HBV-infected HCC specimens, comparing between tumor and non-tumor lesions." (PMID 26766040, 2016).
tumor (continued). "Several factors related with the CSC phenotype, such as ALDH1A1, SOX2, DKK1 and NOTCH1, were increasingly upregulated in the emerging CSC subpopulations during tumor progression." (PMID 27292183, 2016). "The levels of NOTCH1 and PDGFRB in GBM were significantly higher than those in non-tumor controls (P values were 0.0085 or 0.019, respectively), whereas PDGFRA levels were similar (P value was 0.58), consistent with previous reports." (PMID 27863440, 2016). "By meta-analysis, NOTCH1 and NOTCH3 were correlated with tumor progression and poor prognosis in NSCLC." (PMID 27938406, 2016). "NOTCH1 inhibitor DAPT (GSI-IX) significantly reduces CSCs population and tumor self-renewal ability in vitro and in vivo." (PMID 27108536, 2016). "By qPCR we next examined the expression of NOTCH1 and DLL1 in a subset comprising 12 tumor tissues (4 at stage I, 4 at stage II and 4 at stage III) and 6 normal samples, where three were in the proliferative phase and three in secretory phase." (PMID 27039384, 2016). "We further confirmed that NOTCH1 is a direct target of miR-139-5p in CRC cells, and showed that miR-139-5p suppresses tumor growth by downregulating NOTCH1 expression." (PMID 27738333, 2016). "Cetuximab inhibited tumor-induced angiogenesis in vitro and in vivo by significantly downregulating HIF-1α and Notch1." (PMID 25723392, 2015). "Interestingly, GC patients with a larger tumor ( > 5 cm), positive lymphovascular invasion, and distal metastasis had significantly higher expression rates of NOTCH1, thereby suggesting that NOTCH1 may also participate in tumor progression and metastasis of GC." (PMID 26267324, 2015). "Of note, bortezomib reversed tumor-induced downregulation of Notch receptors, Notch1 and Notch2, as well as increased the levels of cleaved Notch intracellular domain (NICD) and downstream targets Hes1 and Hey1 in tumor-draining CD8+T-cells." (PMID 26431276, 2015). "Notch1 and SHH play important and complex roles in the proliferation and differentiation processes of tumor cells." (PMID 26563263, 2015). "Higher expression of Notch1 and Jagged1 mRNA and their proteins were observed in CRC tissues compared to adjacent non-tumor tissue." (PMID 26650241, 2015). "NOTCH1 and NOTCH2 protein expression in pretherapeutic tumor biopsies and response to neoadjuvant chemotherapy." (PMID 25954607, 2015). "Our study highlights the Notch1 pathway as a potential therapeutic target to be manipulated to reprogram and convert CAF to act as tumor suppressors." (PMID 26562315, 2015). "Correspondingly, molecular analysis confirmed the reduced expression of downstream effectors of Notch pathway from tumor xenografts of mice treated with GSI23, demonstrating a potent antitumor efficacy of Notch1 inhibitor." (PMID 25996086, 2015). "One of the most interesting results of our study was the finding of higher expression of cytoplasmic NOTCH1 and of cytoplasmic and nuclear NOTCH2 in early tumor stages (pT1 + pT2), compared to advanced stages (pT3 + pT4)." (PMID 25954607, 2015). "NOTCH1 is found upregulated in CRC and correlates with tumor proliferation, differentiation, lymphatic metastases, and survival time." (PMID 25149074, 2014). "NOTCH1 and JAG1 decreased with increasing tumour stage and became undetectable in several high stage tumours." (PMID 25167871, 2014). "In this study, we investigated gene expression and function of Notch1, EGFR and PDGFR to determine their role among GBM tumor core- (c-CSC) vs. peritumor tissue-derived cancer stem cells (p-CSC) of six cases of GBM." (PMID 25380967, 2014). "Notch activation synergizes with HPV proteins in the transformation of immortalized human keratinocytes and primary keratinocytes, and co-expression of the activated intracellular form of Notch1, along with HPV E6 and E7, can also support tumor growth in vivo." (PMID 25309874, 2014). "Accordingly, Notch1 signaling is up-regulated and activated in embryonal RMS samples and supports the proliferation of tumor cells." (PMID 24797362, 2014).
tumor (continued). "A number of Notch target genes were consistently overexpressed in CYLD defective tumours, including LEF1, HEY1 and NOTCH1." (PMID 25565632, 2014). "The expression level of Notch1 was found to statistically correlate with nuclear grade (P=0.025), TNM stage (P=0.037) and tumor size (P=0.002)." (PMID 24959218, 2014). "RT-qPCR analysis for NOTCH1, NOTCH2, HEY1 and HES1 was conducted on the normal bone/matched OSA and DFI tumor sample sets." (PMID 23816051, 2013). "When combined with Notch1 siRNA in vitro or DAPT in vivo, silybin further decreased the viability of HCC cells and/or inhibited tumor growth." (PMID 24386256, 2013). "Chen’s results strengthen a strong nuclear staining for Notch-1 intracellular domain in lung epithelia, whereas adenocarcinoma samples manifested decreased NICD-1, even undetectable vision in some tumor areas." (PMID 24423157, 2013). "Immunofluorescence for cleaved Notch1 demonstrated Notch activation in vasculature of NGP-LacZ and NGP-LacZ + BV, but a paucity of activation in NGP-N1D and NGP-N1D + BV tumor vessels." (PMID 24066611, 2013). "Specifically, mRNA expression of NOTCH1 and NOTCH2 was elevated in tumor samples compared to normal bone (p < 0.05, q < 0.05)." (PMID 23816051, 2013). "NOTCH1 expression was measured in 16 PGL samples (two, 33PT-1 and 33PT-2, from different areas of the same tumor) and compared to expression in 5 JNs." (PMID 23955600, 2013). "Whole genome shotgun sequencing detected the rearrangements involving several known tumor suppressors in 20 tumor/normal sample pairs, which were further confirmed by RNA sequencing including PTEN, RB1, NOTCH1, NF1, and CDKN2A." (PMID 23109866, 2012). "Transfection with cleaved, active Notch1 (ICN-1) and Jagged-1 resulted in increased VEGF, and Jagged-1 significantly increased tumour cell invasion." (PMID 23226563, 2012). "A role of Notch1 and HEY1 over-expression in embryonal RMS is supported by the inhibition of cell proliferation in tumor cell lines depleted of either Notch1 or HEY1." (PMID 23158439, 2012). "By in silico analysis, miR-34a is predicted to target several members/genes of notch signaling: Notch1, Notch2 and Jagged1, which were reported to play critical roles in EMT of tumor and endothelial cells." (PMID 22363487, 2012). "This work shows that amoeboid tumour cells migrate in stiff matrices by upregulating ROCK1 activity and cell contractility via an epigenetically-derived, Notch1-dependant mechanism." (PMID 22583596, 2012). "Previously, Notch1 was shown to cooperate with the Snail pathway by upregulating Snail transcription, inducing EMT and promoting hypoxia-induced tumor cell invasion." (PMID 22128911, 2011). "However, based on the specific role of Dll4-Notch1 in neovascularization, anti-Dll4, and similarly anti-Notch1 and anti-Notch2 antibodies have been proposed as sharper therapeutic agents devoid of side effects against various tumor types in mouse xenograft models." (PMID 21078177, 2010). "Correlation of RhoC with Notch1 and pAkt was assessed on serial sections of SCC tissues and all the molecules were found to be expressed in the same areas of the various tumour sections." (PMID 19953094, 2010). "In particular, overexpression of NOTCH1, a receptor frequently activated in TNBC, may contribute to enhanced EMT, tumor invasiveness, and maintenance of cancer stem-like cells." (PMID 41463075, 2025). "Notably, while Dio upregulates EGFR expression via the Notch1/Jagged1 pathway in liver regeneration models, it exhibits suppressive effects on EGFR activity in tumor contexts." (PMID 40391080, 2025). "Rather, prior work on NOTCH1 in SCLC has largely focused on the role of NOTCH1 as a tumor suppressor and as a driver of NE to non-NE transdifferentiation." (PMID 40627448, 2025).